POLE (DNA polymerase epsilon, catalytic subunit)
Diseases named in the same sentence as POLE in open-access papers (continued):
Sharing a sentence is not in itself a finding about the gene and the disease.
breast carcinoma (14 papers, 2015 to 2026). "The POLE:c.4259C>T p.(A1420V) variant was detected in a patient with a glioblastoma CNS WHO grade 4 who had had breast cancer four years earlier." (PMID 37990341, 2023). "Six of 43 (14%) female POLE variant heterozygotes developed breast cancer (median age 49 years, range 38–65), as did 4/17 (24%) female POLD1 variant heterozygotes (median age 62 years, range 52–65)." (PMID 33948826, 2022). "Endometrial and breast cancers, and possibly ovarian and brain tumors, are also associated with POLE alterations." (PMID 35812186, 2022). "POLE c.861T>A (p.Asp287Glu) (MAFgnomAD_NFE = 0.17%) was identified in two unrelated breast cancer patients, one of whom was also diagnosed with an MMR-deficient CRC." (PMID 32792570, 2020). "In a family that has colon, gastric and breast tumors, the variants p.Arg1436Gln in POLE and p.Pro2033Ser in ATR were identified in a breast cancer case and in her healthy brother of the index case." (PMID 32522261, 2020). "In family C, as the different cancer cases were deceased, we could only test a healthy brother of the index case who developed breast cancer for the VUS (p.Arg1436Gln in POLE and p.Pro2033Ser in ATR); the two of them carried both variants." (PMID 32522261, 2020). "This signature is thought to be related to defects in POLE and DNA mismatch repair genes and thus suggests that defects in POLE and DNA mismatch repair genes may play a larger role is postM breast cancers than preM." (PMID 26251034, 2015). "Consistent with these prior findings, we did not observe a significant impact on the viability of MCF7 breast cancer cells (known low CDK2 activity) upon POLE suppression." (PMID 40760094, 2025). "A particular case is that of POLE p.Glu396Thrfs*15, identified in four breast cancer–affected women of the same family in absence of additional pathogenic variants in known or candidate hereditary cancer genes (exome sequencing; data not shown)." (PMID 32792570, 2020). "Whilst this is based on only 40 female POLE ED heterozygotes and 17 female POLD1 heterozygotes, we conclude that female POLD1 ED heterozygotes in particular may be at an increased risk of developing breast cancer compared to the general population, but this is not proven." (PMID 33948826, 2022).
colorectal tumors (14 papers, 2014 to 2024). "After colorectal tumours, duodenal tumours were the next most frequent lesions in POLE variant heterozygotes." (PMID 33948826, 2022). "The highest similarity to our HT115 spectrum was found with a particular colorectal tumor sample annotated with stop codon (R1371*) and a missense mutation L1235I in the POLE gene (cosine similarity = 0.97 ± 0.01)." (PMID 30459213, 2018). "Mutations in POLE have been shown to contribute to an ultramutated yet MSS phenotype in colorectal tumors." (PMID 28178681, 2017). "A recent NGS study confirmed that increasing mutational load correlated with MSI yet colorectal tumors with the highest mutational burden that were distinct from MSI tumors all harbored POLE mutations." (PMID 28178681, 2017). "In a clinical setting, deploying this DL model as a preliminary screening tool could facilitate the efficient identification of clinically relevant MSI and POLE mutations in colorectal tumors, in one go." (PMID 38783059, 2024). "Cancer driver mutations found in crypts from normal intestine, and colorectal neoplasms from individuals with POLE/POLD1 germline mutations, showed SBS and ID mutational spectra similar to genome-wide spectra from normal intestinal crypts from these individuals." (PMID 34594041, 2021). "Colorectal tumors from patients with a germline pathogenic POLE variant (i.e., variant leading to loss of the proofreading function of the polymerase) are usually MSS, but germline variants in POLE were sometimes reported in patients with early-onset MSI/dMMR CRC and somatic variants in MMR genes." (PMID 33530449, 2021). "Five colorectal tumours from three affected individuals were all microsatellite stable (MSS) which is in line with previous findings that tumours with mutations in POLE are MSS and are hypermutated with mutations in other genes involved in the classical tumorigenesis pathway." (PMID 24788313, 2014). "In addition, although we did not have the statistical power to demonstrate an association with TILs in POLE-mutated colorectal tumors, we speculate that they could be responsive to checkpoint inhibition based on their increased neoantigen load." (PMID 27149842, 2016). "In the spectrum of colorectal tumors, microsatellite-stable (MSS) tumors with DNA polymerase ε (POLE) mutations exhibit a hypermutated profile, holding the potential to respond to immunotherapy similarly to their microsatellite-instable (MSI) counterparts." (PMID 38783059, 2024). "As such, somatic mutations in POLE represent a mechanism that can lead to highly immunogenic colorectal tumors with an ultra-mutated phenotype that is independent of the mismatch repair status." (PMID 37239414, 2023).
adenoma (13 papers, 2014 to 2025). A neoplasm arising from the epithelium. "Most colorectal polyps were tubular or tubulovillous adenomas, although nine POLE and five POLD1 variant heterozygotes also had hyperplastic polyps." (PMID 33948826, 2022). "Having such a high mutation burden, the case A16 was presumed to have mutations in POLE, because the adenoma and cancer mutational spectra matched signature 10 in the COSMIC database." (PMID 29467928, 2018). "Therefore, increases in SBS and ID mutation rates are associated with conversion from a normal crypt to an adenoma or cancer crypt in individuals with POLE or POLD1 germline mutations, a pattern similar to that observed in healthy individuals." (PMID 34594041, 2021). "Furthermore, a quantitative analysis of POLE wild type allele showed a significant decrease of POLE expression in all tested carrier’s adenomas and adenocarcinoma, which is consistent with a replicative stress due to POLE haploinsufficiency." (PMID 31285513, 2019). "In the case of POLE, tumour and normal tissue data, as well as evidence in yeast, indicate that polymerase ε proofreading deficiency is haploinsufficient, not requiring the inactivation of the second allele to promote DNA damage (hypermutation) and adenoma/cancer initiation." (PMID 40237887, 2025). "A missense somatic mutation call in POLE with an AF of 0.25 in the cancer sample of the A16 case may account for only a part of the story, since the mutational spectra tell us that the mutations in POLE gene happened early in the evolution for such patterns to form both in adenoma and in cancer." (PMID 29467928, 2018). "Therefore, we discarded the involvement of the NTHL1 monoallelic mutation c.268C > T p.(Gln90*) in the polyposis predisposition of this patient and we considered the possibility that POLE:c.141delG p.Phe48Leufs*6 could confer the adenoma predisposition by itself." (PMID 31285513, 2019). "Interestingly, in 12 samples (11 adenomas and 1 in situ carcinoma), POLE (c.T1166C:p.F389S) VUS was identified." (PMID 35173208, 2022). "The elevated mutation loads in adenoma and carcinoma crypts from POLE/POLD1 germline mutation carriers compared to normal intestinal crypts from each individual were also predominantly due to increased burdens of SBS10a and 10b (in POLE-mutant cases) and SBS10c and SBS10d (in POLD1-mutant cases)." (PMID 34594041, 2021). "Other works analyzing AAP cohorts, such as Grover30 who analyzed MUTYH and APC in 4223 patients with 10 to 100 adenomas, or Stanich20 who also analyze POLD1 and POLE and other CRC genes in 2979 patients with 10 to 100 adenomas, showed similar clinical results." (PMID 31285513, 2019). "The difference in frequency of CRCs and adenomas was not significantly different between POLE and POLD1 heterozygotes (Fisher’s exact test, CRC p = 0.12, CRA p = 0.19)." (PMID 33948826, 2022). "Patients who carry EDMs in POLE or POLD1 show variable phenotypes: some have tens of adenomas that do not appear to progress rapidly to cancer, whereas others have a small number of large adenomas or early-onset carcinomas, thus resembling Lynch syndrome." (PMID 24583393, 2014). "However and unlike POLE, NTHL1 expression was increased in two of the carrier’s adenomas and adenocarcinoma tissues." (PMID 31285513, 2019).
endometrioid tumor (13 papers, 2014 to 2026). A benign, borderline, or malignant epithelial tumor of the female reproductive system characterized by the presence of glands and/or cysts lined by neoplastic cells that resemble endometrial cells. "There was an enrichment of high-grade endometrioid tumors, to ensure a good representation of POLE-mutated tumors, which accounted for 21.8% of the cases." (PMID 37874375, 2023). "POLE-ultramutated subgroup characterized by pathogenic POLE exonuclease domain mutations is composed of endometrioid tumors and associated with the most favorable prognosis." (PMID 36003784, 2022). "Overall, somatic mutations within the exonuclease domain of POLE were detected in 2.2% (1 of 45) of serous, 4.8% (1 of 21) of clear cell, and 2.4% (1 of 41) of endometrioid tumors in our cohort." (PMID 25427824, 2014). "Endometrioid tumors are characterized by DNA polymerase epsilon catalytic subunit (POLE) mutations, microsatellite instability (MSI; impaired DNA mismatch repair of repeat DNA sequences of typically 1–6 base pairs [microsatellites]), and copy-number low/microsatellite stable (MSS) status." (PMID 37839313, 2023). "Likewise, POLE-positive cases were detected in only endometrioid tumors as ARID1 mutations, which mainly appeared in endometrioid histology." (PMID 32098121, 2020). "Endometrioid tumors are characterized by β-catenin alterations, microsatellite instability, and PTEN and POLE mutations, while ARID1A mutations occur in both endometrioid and clear cell carcinomas." (PMID 33919741, 2021). "They showed that endometrioid tumors mostly belong to the POLE, MSI, and CNL groups." (PMID 36233549, 2022). "Second, a small but significant fraction of endometrioid tumors display mutations in the proofreading domain of POLE, and mutations are not found in other non-serous subtypes." (PMID 28852190, 2017). "Other altered genes labelling the endometrioid cancer were CTNNB1, KRAS, POLE, and ARID1A genes, each of them accepted as genetic biomarker of the endometrioid tumors." (PMID 36010253, 2022).
gastric cancer (13 papers, 2016 to 2025). A primary or metastatic malignant neoplasm involving the stomach. "A retrospective gastric cancer cohort study revealed the total frequency of POLE mutations was 7.99%." (PMID 37048719, 2023). "Twenty-four hyper-mutated tumors were identified only in colorectal and gastric cancers, with a significant enrichment of mutations in the polymerase genes (POLE, POLD1, and POLH) and mismatch repair (MMR) genes." (PMID 34594355, 2021). "We cannot completely exclude the possibility that our patient had a POLE-mutated tumor; however, the incidence of POLE mutation in gastric cancer is very low (0.47 %) and TILs in the tumor microenvironment were scant in our patient." (PMID 27012666, 2016). "The fraction of A→G mutations was increased in stomach cancers with concurrent mutations on POLD1 and POLE genes." (PMID 28582771, 2017). "The POLE mutation was an independent indicator for predicting survival benefits from immunotherapy, independent from MSI, which is also listed as one of the molecular subtypes of gastric cancer in the cBioportal database." (PMID 34828321, 2021). "Our results illustrated that a simple log-transformation of TMB in colorectal, endometrial, and stomach cancers could also reveal POLE-driven and MSI-driven tumors." (PMID 32188929, 2020). "Moreover, POLE mutations were associated with dMMR, PD-L1 overexpression, and TMB-H, suggesting they might be a specific biomarker for advanced gastric cancer." (PMID 37048719, 2023). "Furthermore, signature 28, often found in cancers with mutations in POLE, continued to be generated in all of these cell lines but not in the examined stomach cancer cell line (AGS)." (PMID 30849372, 2019). "Among the most highly significant genes were all those previously reported in the context of the hypermutator phenotype of gastric cancer, including POLD1 (p-value < 10−11), POLE, KMT2C, KMT2A (p-value < 10−8), and MLH1 (p-value < 10−4)." (PMID 41301688, 2025). "Future studies can examine the POLQ knockdown in stomach cancer cell lines with concurrent defects of POLD1 and POLE." (PMID 28582771, 2017). "In the Venn diagram intersection of recognized targets about identified chemical compounds and gastric cancer, a total of 23 gastric cancer genes are acquired among which the top six genes ABCG2, MUTHY, TRET, POLE, BRAF and G, and FGFR2 were used to produce Venn diagram." (PMID 36500601, 2022). "However, we observed that a POLE p.A1778V mutation in patient #GA_59, who developed gastric cancer at age 76 with a TMB of 45 (71% were missense mutations), was the only mutation in the polymerases and MMR genes in this patient, suggesting that this mutation might impair POLE function." (PMID 34594355, 2021).
brain tumors (12 papers, 2018 to 2026). "CMMRD high grade brain tumours are often (ultra-)hypermutated due to somatic POLE or POLD1 exonuclease domain variants that impair polymerase proofreading, leading to a complete loss of replication error repair." (PMID 38789506, 2024). "In our summary of 37 brain tumor patients carrying rare POLE/POLD1 germline variants, oligodendrogliomas were found in as many as 13.5% of cases." (PMID 37990341, 2023). "In line with our findings, a recent report summarizing 132 carriers of probably pathogenic POLE/POLD1 germline exonuclease domain variants identified 10 (8%) brain tumor cases among these patients." (PMID 37990341, 2023). "At least two brain tumors were observed in six of the 10 (60%) families with rare POLE or POLD1 germline variants." (PMID 37990341, 2023). "Brain tumours have also now been reported in nine of 105 (9%) of POLE variant heterozygotes." (PMID 33948826, 2022). "Of note, concurrent MMRD and PPD is seen in the majority of CMMRD-associated malignant brain tumors and approximately one third of CMMRD-associated gastrointestinal cancers, due to the biallelic germline MMR PV along with somatic POLE/POLD1 PV." (PMID 39031223, 2024). "Nine patients with POLE pathogenic variants and one with a POLD1 pathogenic variant developed brain tumours." (PMID 33948826, 2022). "Another possible option that would allow the identification of CMMRD in brain tumors would be sequencing to determine MSI, mutation burden and signatures, and other alterations characteristic of these tumors, such as POLE or POLD1 variants." (PMID 33924881, 2021). "Pediatric CMMRD patients presenting with brain tumors commonly have biallelic loss of PSM2 or MSH6, ultra-hypermutated pediatric GBM, and a unique MMR first/POLE second mutational signature." (PMID 31604779, 2019). "Pathogenic variants in POLE or POLD1 causing defective polymerase proofreading, and pathogenic variants in MMR genes causing defects in MMR can lead to a high TMB, i.e. hypermutation, in the DNA of human tumors, including brain tumors, when they occur in the germline or somatically." (PMID 37990341, 2023). "Therefore, the analysis of POLE and POLD1 genes in the brain tumor DNA sample from patient III-2 revealed the presence of four variants in POLD1." (PMID 33924881, 2021).
glioblastoma (12 papers, 2018 to 2026). The most malignant astrocytic tumor (WHO grade IV). "The POLE:c.776G>A p.(R259H) variant was identified in a total of three patients from two families who were affected by glioblastomas CNS WHO grade 4 or small cell lung cancer." (PMID 37990341, 2023). "When considering only the six POLE/POLD1 variant carriers with a glioblastoma CNS WHO grade 4, their mean age was 59 years and their mean overall survival was 21 months." (PMID 37990341, 2023). "They identified 12 tumors (5 CRC, 6 endometrial and 1 glioblastoma) with bona fide functional POLE mutations." (PMID 37388540, 2023). "In the single viable LN-229 glioblastoma clone with a POLE knockout, a mutator phenotype was observed." (PMID 37990341, 2023). "Taken together, rare POLE variants were identified in two of four (50%) glioblastoma patients who developed spinal metastases." (PMID 37990341, 2023). "In a CRISPR/Cas9-derived POLE-deficient LN-229 glioblastoma cell clone, a mutator phenotype and delayed S phase progression were detected compared to wildtype POLE cells." (PMID 37990341, 2023). "Despite the small number of patients, data from us and others suggest an increased risk of spinal metastases in glioblastomas with rare POLE variants." (PMID 37990341, 2023). "Our data suggest that DNA polymerase δ function is essential in glioblastoma cells, and that loss of POLE impacts mutation rate, cell cycle progression, and glioblastoma cell survival." (PMID 37990341, 2023). "The only viable POLE KO LN-229 glioblastoma clone was characterized by impaired S phase progression and a mutator phenotype compared to a POLE WT LN-229 glioblastoma clone." (PMID 37990341, 2023). "In another case report, a glioblastoma patient with germline PolE V424L mutation showed a good response to immunotherapy with pembrolizumab." (PMID 35326618, 2022). "Different from somatic PolE mutations, ultramutated glioblastoma with the germline PolE V424L mutation is predominated by C > G transversion." (PMID 35326618, 2022). "Owing to its rarity, clinical trial to evaluate the ICI efficacy in POLE-mutated glioblastoma is very challenging." (PMID 34345822, 2021). "Here, we report a case of recurrent POLE-mutated glioblastoma with response to pembrolizumab and bevacizumab." (PMID 34345822, 2021). "Rare cases of IDH-wildtype glioblastoma occurring in adult patients with similar proofreading domain missense mutations in POLE, ultrahypermutation, and response to immune checkpoint blockade have also been reported, although their precise frequency remains uncertain." (PMID 38079020, 2023). "Glioblastoma patients carrying rare POLE variants had a mean overall survival of 21 months." (PMID 37990341, 2023). "To assess whether POLE deficiency affects mutation rate in glioblastoma cells, we performed a HPRT1 mutation assay in POLE WT and KO LN-229 glioblastoma cells." (PMID 37990341, 2023). "Similarly, the mean overall survival of 21 months observed here in POLE/POLD1 germline variant carriers with a glioblastoma compares favorably with the median overall survival of 8 months for glioblastomas according to a recent CBTRUS Statistical Report." (PMID 37990341, 2023). "In a subset of the de novo RRD glioblastomas (3/9, 33%), the mismatch repair deficiency was accompanied by a somatic POLE missense mutation in the proofreading domain of the encoded DNA polymerase epsilon: p.A456P, p.S461P, and p.V411L (annotated per RefSeq transcript NM_006231)." (PMID 38079020, 2023). "This may explain why we identified rare POLE variants in two of four (50%) glioblastoma patients who developed spinal metastases, and another case was reported previously, whereas spinal metastases normally develop in only around 1% of glioblastoma patients." (PMID 37990341, 2023).